PCAT18 (prostate cancer associated transcript 18)
Synonyms: LINC01092
Gene: Long non-coding RNA gene on chromosome 18 (26,658,954 to 26,703,783, reverse strand). Ensembl gene ENSG00000265369.
Gene Ontology:
Biological process: RNA processing
Cellular component: nucleolus
Diseases named in the same sentence as PCAT18 in open-access papers:
PCAT18 is named in the same sentence as 17 diseases in open-access papers, as found by Europe PMC text mining. Sharing a sentence is not in itself a finding about the gene and the disease. The quoted sentences say what the papers report.
prostate carcinoma (14 papers, 2014 to 2023). A carcinoma that arises from epithelial cells of the prostate gland. "Prostate cancer associated transcript 18, also known as PCAT-18, is a 2.5-kb non-coding RNA with two exons and is located on chromosome 18q11.2." (PMID 29755696, 2018). "The prostate cancer associated transcript 18 (PCAT18) gene located at 18q11.2 is highly expressed in prostate cancer." (PMID 30518158, 2018). "LncRNA prostate cancer-associated non-coding RNA transcript 18 (PCAT-18) identified by RNA sequencing is specifically expressed in prostate tissue, and upregulated in prostate cancer compared to other neoplasms and BPH tissues." (PMID 28272371, 2017). "Similarly, PCAT-18 (prostate-cancer-associated non-coding RNA transcript 18 and SChLAP1 (second chromosome locus associated with prostate-1)) has also been used as a diagnostic and prognostic biomarker in PCa." (PMID 37218885, 2023). "PCAT18 was found to be associated with the progression of gastric cancer and prostate cancer." (PMID 31850052, 2019). "Previous studies indicated that in metastatic prostate cancer, PCAT18 is strongly expressed and that knockdown of PCAT18 obviously suppressed proliferation and migration of the prostate cancer cells." (PMID 34729108, 2021). "PCAT18 is also abnormally expressed in migratory prostate cancer and can be used as a potential therapeutic target for the treatment of metastatic prostate cancer." (PMID 34787047, 2021). "One previously characterized lincRNA (RP11_321F6.1, also known as PCAT18), is shown to be a regulator of prostate cancer cell proliferation, invasion and migration." (PMID 28467780, 2017). "PCAT-18 (prostate cancer-associated noncoding RNA transcript 18), a long noncoding RNA, was recently discovered by RNA sequencing; PCAT-18 exhibits a highly specific expression pattern in prostate cancer." (PMID 26110379, 2015). "It is of note that it is also recently reported that PCAT18 is a highly prostate-specific transcript, upregulated in prostate cancer, and that the expression of PCAT18 is induced by AR signaling." (PMID 25243154, 2014). "For example, the level of long non-coding RNA-activated by transforming growth factor β (ATB) was increased by 5–10-fold in glioma patients, while that of a metastatic prostate cancer-related lncRNA PCAT18 was reported to be elevated by 8.8–11-fold in prostate cancer cells." (PMID 36768958, 2023). "For example, PCAT18 silencing inhibited prostate cancer proliferation, migration, and invasion." (PMID 31850052, 2019). "Therefore, lncRNA PCAT18 is also an important target for evaluating the occurrence and therapeutic effect of adenocarcinoma, such as gastric adenocarcinoma and prostate cancer; however, its role and function in TNBC has not yet been reported." (PMID 34787047, 2021).
gastric cancer (9 papers, 2018 to 2025). A primary or metastatic malignant neoplasm involving the stomach. "lncRNA PCAT18 expression has a significant effect in tissue-specific downregulation in gastric cancer compared to normal tissues and can be used as a diagnostic factor for gastric cancer." (PMID 34787047, 2021). "A previous study reported that prostate cancer-associated transcript 18 (PCAT-18), a long non-coding RNA, interacted with CCDC32 as a tumor suppressor in gastric cancers." (PMID 39823827, 2025). "For example, PCAT18 expression is downregulated in gastrointestinal tumor tissues, including gastric cancer." (PMID 38336706, 2024). "Alteration of PCAT18 expression causes the impairment of colorectal cancer (CRC) and gastric cancer proliferation." (PMID 34787047, 2021). "PCAT18 can upregulate TP53INP1 expression to inhibit metastasis of gastric cancer by sponging miR-301a." (PMID 34787047, 2021). "The expression of lncRNA PCAT18 is negatively correlated with the size of the gastric tumor, and the upregulation of lncRNA PCAT18 can significantly inhibit the proliferation and tumor growth of gastric cancer cells." (PMID 34787047, 2021). "In the present study we observed a down-regulation of PCAT18 in GC/stomach cancer tissues pointing to a role of this lncRNA in GC development." (PMID 30518158, 2018). "Moreover, several previous studies have indicated that PCAT18 could inhibit the proliferation, migration, and invasion of gastric cancer (GC) cells, which could provide a theoretical basis for GC therapy." (PMID 36620596, 2022). "The current study aimed to determine the expression, clinicopathological characteristics and functional roles of lncRNA PCAT18 in gastric cancer (GC)." (PMID 34729108, 2021). "For further validation TCGA RNA-seq expression data for PCAT18, DANCR, and LINC01133 in stomach cancer and normal tissues were analyzed." (PMID 30518158, 2018). "The expression of PCAT18 and LINC01133 was down-regulated in stomach cancer tissues (p = 6.35 × 10−19 and p = 0.3.40 × 10−7, respectively; validation 3)." (PMID 30518158, 2018). "For instance, two tissue-specific lncRNAs, PCAT18 and LINC01133, were enriched in normal stomach tissues and downregulated in gastric cancer (GC)." (PMID 35101062, 2022).
metastatic prostate carcinoma (6 papers, 2016 to 2024). A carcinoma that arises from the prostate gland and has spread to other anatomic sites. "PCAT-18 was first discovered to be as a factor involved in invasion, migration, and growth of metastatic prostate cancer." (PMID 38336706, 2024). "PCAT-18 was recently suggested as a biomarker for metastatic prostate cancer, and knockdown of PCAT-18 decreased cell proliferation, migration, and invasion but also triggered apoptosis by promoting caspase activity." (PMID 27191265, 2016).
breast carcinoma (2 papers, 2018 to 2021). "Notably, ATF7 expression was positively associated with PCAT18 expression in both breast cancer tissues and TNBC-specific specimens." (PMID 34787047, 2021). "The PCAT18/miR-103a-3p/ATF7 signaling axis was also demonstrated in a lung metastasis model of breast cancer." (PMID 34787047, 2021). "Indeed, PCAT18 upregulation mediated the improvement in lung metastasis in breast cancer, which was also aided by injection of miR-103a-3p mimic, followed by the decline in ATF7." (PMID 34787047, 2021). "Based on the analysis of ENCORI Starbase, no differential expression of PCAT18 was observed between samples from normal subjects (n = 113) and those from patients with breast cancer (BRCA, n = 1104)." (PMID 34787047, 2021). "However, PCAT18 is also abnormally expressed in HER2-E and luminal A/B subtypes of breast cancer." (PMID 34787047, 2021).
colorectal cancer (2 papers, 2021). A primary or metastatic malignant neoplasm that affects the colon or rectum. "Colorectal cancer (CRC) is an example where the expression of SPRR3 promotes the binding between PCAT18 and miR-759 and therefore restores a portion of the proliferation and invasion capabilities of CRC cells." (PMID 34235216, 2021).
gastric tumor (2 papers, 2018 to 2021). "The down-regulation of PCAT18 and LINC01133 in GC implies that these lncRNAs may have a tumor suppressive function in the development of gastric tumors." (PMID 30518158, 2018).
acute myeloid leukemia (1 paper, 2021). Acute myeloid leukemia (AML) is a group of neoplasms arising from precursor cells committed to the myeloid cell-line differentiation. "PCAT18 is upregulated in acute myeloid leukemia (AML) samples and may act as a diagnostic and prognostic biomarker for AML." (PMID 34787047, 2021).
benign prostatic hyperplasia (1 paper, 2014). A non-cancerous nodular enlargement of the prostate gland. "Cancer-specific up-regulation of PCAT18 was confirmed on an independent dataset of PCa and benign prostatic hyperplasia samples (p<0.001)." (PMID 24519926, 2014).
colon adenocarcinoma (1 paper, 2019). "By analyzing the GEPIA database, we found that the expression levels of MIR100HG, SERTAD4-AS1, and PCAT18 were significantly downregulated; however, KRTAP5-AS1 was upregulated in both colon adenocarcinoma (COAD) and rectum adenocarcinoma (READ) samples compared with that in normal tissues." (PMID 31850052, 2019).
cancer (9 papers, 2014 to 2025). A tumor composed of atypical neoplastic, often pleomorphic cells that invade other tissues. "Long non-coding RNA (lncRNA) prostate cancer-associated transcript 18 (PCAT18) is a potential diagnostic target for adenocarcinoma." (PMID 34787047, 2021). "In light of these data, this gene was officially named PCAT18 (Prostate Cancer-Associated Transcript-18) by the HUGO Gene Nomenclature Committee." (PMID 24519926, 2014). "The expression of PCAT18 has been found to vary across different cancer types, highlighting the complexity of the molecular landscape among different tumors." (PMID 38336706, 2024). "Single cell-based approach to understand the role of PCAT18 in cancer development and progression may provide more substantial answer to these contradictory results." (PMID 38336706, 2024). "The role of PCAT18 in cancer progression remains controversial." (PMID 38336706, 2024). "PCAT18 acts as a cancer inhibitor by impairing the viability, invasion, and migration of GC cells." (PMID 35101062, 2022). "Similar to PCAT18, LINC01133 is also highly expressed in normal stomach tissues based on GTEx data implying that its deregulation in normal stomach tissue may play a role in the fate of cells and cancer progression." (PMID 30518158, 2018).
tumor (7 papers, 2014 to 2025). "Tumor heterogeneity can influence the expression patterns of PCAT18, while cellular context can influence its function." (PMID 38336706, 2024). "Another repressed lncRNA in GC is PCAT18, whose downregulation was shown to induce greater cell proliferation and cell cycle progression, and lower apoptosis in vitro, as well as increased tumor growth in vivo." (PMID 37047267, 2023). "The expression of PCAT18 was significantly downregulated in 90% (54 of 60) of the GC tissues in contrast to tumor-free tissues." (PMID 34729108, 2021). "During the current study, we discovered that PCAT18 was significantly lower in GC tissues in contrast to non-tumor tissues." (PMID 34729108, 2021). "Approximately 22 tumor nodules were detected in the vector-administered model group, while nine nodules were found in the PCAT18-overexpressed group." (PMID 34787047, 2021). "Development of the tumor was significantly delayed in the overexpression PCAT18 group in contrast to the control group." (PMID 34729108, 2021). "PCAT18 is specifically expressed in the prostate compared to 11 other normal tissues (p<0.05) and up-regulated in PCa compared to 15 other neoplasms (p<0.001)." (PMID 24519926, 2014). "The levels of PCAT18 were also related to the tumor's TNM stages (p=0.004)." (PMID 34729108, 2021). "Therefore, both GAS5 and PCAT18 may also be proposed as potential tumor suppressor lncRNAs in GC and could be explored to be used in GC treatment." (PMID 37047267, 2023). "Moreover, tumor weight significantly decreased in the PCAT18-overexpressed group compared to the control group, while miR-103a-3p mimic management notably counteracted the anti-tumor growth effect produced by PCAT18 overexpression." (PMID 34787047, 2021). "Regarding downregulated lncRNAs, GAS5 and PCAT18 have been inversely correlated with advanced TNM stage and greater tumor size, respectively." (PMID 37047267, 2023). "The relationship between expression of PCAT18 and LINC01133, overall survival and tumor grade/stage was investigated using the The Cancer Genome Atlas- Stomach Adenocarcinoma (TCGA-STAD) dataset." (PMID 30518158, 2018). "The heuristic potential of our analysis is confirmed by the characterization of a lncRNA (PCAT18), whose function in human neoplasms had never been described before." (PMID 24519926, 2014). "Our findings of a tissue-specific down-regulation of PCAT18 and LINC01133 in gastric and other gastrointestinal cancers imply that these lncRNAs may have a tumor suppressive function in the development of these tumor entities." (PMID 30518158, 2018).
gastrointestinal tumor (2 papers, 2018 to 2024). "Altogether, we showed a decreased tissue-specific expression of PCAT18 and LINC01133 lncRNAs in GC and other gastrointestinal tumor tissues, suggesting a role of these lncRNAs in the development of gastrointestinal tumors." (PMID 30518158, 2018).
PCAT18 also shares sentences with these, for which no sentence is quoted: adenocarcinoma (2 papers); acute leukemia (1); metastatic disease (1); prostate tumors (1); rectum adenocarcinoma (1).